IFNG (interferon gamma)
Diseases named in the same sentence as IFNG in open-access papers (continued):
Sharing a sentence is not in itself a finding about the gene and the disease.
tuberculosis (continued). "The result of interferon gamma release assay from tuberculosis-infected T cells (TB-IGRA) was indeterminate." (PMID 37904420, 2023). "Studies have shown that hypermethylation of the IL12RB (Interleukin 12 Receptor Subunit Beta) genes can lead to the reduction of tuberculosis-specific production of the cytokine interferon gamma (IFNγ)." (PMID 37175405, 2023). "Therefore, we evaluated the association between the IFNG +874 A/T genotypes and the levels of this cytokine produced by M. tuberculosis-stimulated PBMCs from HD and TB patients." (PMID 36743307, 2023). "This view is supported by a recent study showing that P2RX7 expression in CD4+ T cells is particularly important for cell migration, proliferation and production of IFNγ in the pulmonary parenchyma during severe tuberculosis and influenza." (PMID 36993971, 2023). "tuberculosis interferon-gamma release assay test and Mantoux test, making the diagnosis of ocular tuberculosis more likely." (PMID 37850223, 2023). "In a cohort of 74 HIV-negative patients with anti-IFNγ auto-antibodies from the USA and Thailand, with almost all the American patients being of Asian descent, 5 diagnoses of tuberculosis were made (two pulmonary and three disseminated cases)." (PMID 38203686, 2023). "In particular, Cas6, provokes interferon gamma (IFN-γ) release from the peripheral blood mononuclear cells of patients with active tuberculosis, and its deletion markedly attenuated virulence in a murine MTB challenge model." (PMID 38090672, 2023). "In a case-control study we genotyped the IFNG +874 A/T SNP in 199 healthy donors (HD) and 173 tuberculosis (TB) patients enrolled between 2012 and 2016." (PMID 36743307, 2023). "In this study, we analyzed the concentrations of selected plasma cytokines (i.e., IL-6, IP-10, IL-10, IL-22, IFNγ, GM-CSF, IL-8) and M. tuberculosis sputum burden in patients with tuberculosis (n = 76)." (PMID 35759173, 2023). "The interferon system, particularly the role of interferon-gamma, has been identified as the main link in the immune response in tuberculosis." (PMID 35360672, 2022). "Database for results of interferon gamma release assay (IGRA), X-ray, and baseline demographic information was linked with National Health Information Database, national tuberculosis (TB) surveillance database, and national contact investigation database." (PMID 36743163, 2022). "Recent experimental data make it possible to consider interferon-gamma as a promising therapeutic option for the treatment of multidrug-resistant tuberculosis as part of complex therapy worthy of further studies." (PMID 35360672, 2022). "Interferon-gamma (IFN-γ), an important cytokine, can act as an early indicator of infectious diseases, such as tuberculosis." (PMID 36080490, 2022). "Currently, T-cell based interferon-gamma (IFN-γ) release assays (IGRA) have progressively been used to subtitute tuberculin skin test (TST) as an instrument to diagnose tuberculosis." (PMID 35227196, 2022). "Screening tests for latent tuberculosis by chest radiographic imaging and interferon gamma release assays for tuberculosis/PPD skin tests are mandatory before initiating TNF inhibitors in intermediate to high-burden areas for tuberculosis." (PMID 36430392, 2022). "All people living with HIV should be screened for tuberculosis (TB) at the time of their initial diagnosis with either a tuberculin skin test (TST) or with an interferon gamma release assay (IGRA)." (PMID 35456055, 2022). "In AC treated SjSS BMDMs, pathways involving host defense were upregulated, involving pathways for tuberculosis, viral, and influenza A. IFNβ, IFNγ, and TNF pathways were all elevated, indicating overactivated inflammatory cytokine signaling." (PMID 35597820, 2022). "Examination for tuberculosis (tuberculin skin test, interferon gamma release assay, chest radiograph, and computed tomography) before CT‐P13 administration was performed in all but one patient." (PMID 35799412, 2022).
tuberculosis (continued). "In PBMC cultures of both healthy donors and tuberculosis patients, the highest IFNγ response to 24 h sonicate stimulation was detected among CD56dimHLA-DR+ NK cells, compared to CD56dimHLA-DR− and CD56brightHLA-DR+ NK cells." (PMID 34012446, 2021). "The value of Interferon-gamma release assays (IGRA) in the diagnosis of active tuberculosis remains controversial." (PMID 34074288, 2021). "Routine microbiological tests were performed, and tuberculosis interferon gamma release assays were positive." (PMID 34243811, 2021). "We investigated longitudinal whole blood transcriptional profile responses to PT of Interferon gamma release assay (IGRA)-positive tuberculosis contacts and IGRA-negative, tuberculosis-unexposed controls." (PMID 33524936, 2021). "Blood and urine samples were collected from HIV-positive women for cluster-of-differentiation-4 cell count, interferon gamma release assay and tuberculosis lateral flow urine lipoarabinomannan tests." (PMID 32832404, 2020). "Combined with the ability of Bac5 to recruit macrophages and neutrophils, the stimulation of IFNγ production from alveolar macrophage-like cells suggests a potential therapeutic application for Bac5 in the treatment of tuberculosis." (PMID 33352656, 2020). "For this reason, the interferon gamma release assay (IGRA) in response to M. tb antigen stimulation is an alternative approach for tuberculosis diagnosis." (PMID 32883961, 2020). "In this experiment we evaluated antigen-specific IFNγ responses following ex vivo stimulation of lung cells with a preparation of tuberculosis antigens (Purified Protein Derivative, PPD)." (PMID 33347499, 2020). "In the IFX group, IFX was withdrawn in five patients (17%), including three females with infusion reaction, a male with seroconversion of the interferon-gamma release assay (a marker for tuberculosis), and another male with pneumocystis pneumonia." (PMID 32719413, 2020). "Tuberculosis screening was performed through interferon gamma release (QuantiFERON) assay in most (82%) cases, while 12% utilize the Mantoux intradermal test; in one of the centers, a chest X-ray was also routinely performed before the start of ruxolitinib." (PMID 31832751, 2020). "Commercially available ELISA systems for the detection of tuberculosis are based on the interferon gamma release assay (IGRA)." (PMID 33086578, 2020). "US guidelines have recommended testing children emigrating from high tuberculosis-incidence countries with interferon-gamma release assays (IGRAs) or tuberculin skin tests (TSTs)." (PMID 32687465, 2020). "For example, the IFNγ-release assay (IGRA) uses tuberculosis antigens to stimulate CD4+ T cells and measures the level of IFNγ release to determine previous tuberculosis exposure." (PMID 31581724, 2019). "Previous publications have reported that IFNγ-producing and bifunctional/polyfunctional CD4+ T cells are associated with protection from tuberculosis in experimental models." (PMID 31120957, 2019). "Contrary to our findings, M. tuberculosis lineage 3 sub strain infections have been associated with different phenotypes for instance, reduced expression of TNFα and IFNγ, reduced growth rate in macrophages, causing cavitary TB, pan sensitivity to anti-TB drugs and causing severe disease." (PMID 31498808, 2019). "In our current work, we performed tuberculosis specific interferon-gamma release assays (IGRA, Quantiferon) to assess the latent or active TB infection in a large, unselective subset of refugees representative of the current refugee crisis in Western Europe." (PMID 29904012, 2018). "In tuberculosis, IFNG produced by Th1 cells activates macrophages, which results in the stimulation of phagocytosis, phagosome maturation, the production of reactive nitrogen intermediates and antigen presentation." (PMID 29985419, 2018).
tuberculosis (continued). "Interferon gamma (IFNG) plays a key role during Mycobacterium tuberculosis (Mtb) infection, and several polymorphisms located in its gene are associated with risk of tuberculosis in diverse populations." (PMID 29361774, 2018). "In tuberculosis, Interferon-gamma release assays (IGRAs) are important for the diagnosis of Mycobacterium tuberculosis infections." (PMID 28241036, 2017). "Assays developed for adults such as the interferon-gamma release assay for tuberculosis show inferior performance in children." (PMID 29259216, 2017). "The in vitro measurement of IFNγ production, such as in the Cervigam assay, served as a useful test for the antemortem diagnosis of tuberculosis in Cervidae." (PMID 29145844, 2017). "The identification of rs9828868 as a genetic driver of IFNγ production in response to mycobacterial antigens provides new insights into human anti-tuberculosis immunity." (PMID 28993696, 2017). "The OT-WCA IFN-γ ELISpot assay uses the same technology platform as the T-SPOT interferon-gamma release assay (IGRA) developed for diagnosis of tuberculosis." (PMID 28892515, 2017). "Compared to the baseline, 116 (87.2%) cases had a decreased response, and 17 (12.8%) had persistent interferon-gamma (IFN-γ) responses at 2 months after having positive test cultures and at the end of an intensive phase of anti-tuberculosis treatment." (PMID 28264462, 2017). "PICO question: What is the sensitivity and specificity of interferon gamma release assays compared with the tuberculin skin test for tuberculosis in children < 5 years of age?" (PMID 29019317, 2017). "Interferon-gamma (IFNG) and its receptor (IFNGR1) are principal genes that associated with tuberculosis." (PMID 29228700, 2017). "Sixteen patients were positive for AFB staining and culture, tuberculosis polymerase chain reaction testing, and interferon-gamma." (PMID 29033887, 2017). "Extrapulmonary tuberculosis requires tissue sampling and culture and screening pregnant women with symptoms is often provoked by a positive tuberculin skin test or interferon-gamma release assay." (PMID 27729022, 2016). "Respiratory tuberculosis is one of the diseases characterized granuloma formation which was controlled by cellular immune reactions, interferon-gamma (INF-gamma) which mediate inflammatory reactions increased in the tuberculosis." (PMID 28005963, 2016). "This is in accordance with a wide array of literature describing the crucial role of IFNγ during tuberculosis." (PMID 27519524, 2016). "Interferon-gamma levels (P < 0.0001) and interferon-gamma to interleukin-10 (P < 0.001) and interferon-gamma to adiponectin (P = 0.027) ratios were elevated in tuberculosis cases." (PMID 26880909, 2016). "Even in low tuberculosis incidence countries, screening for tuberculosis infection with an interferon-gamma release assay is considered cost effective." (PMID 27729022, 2016). "Patients with TS had more previous histories of tuberculosis (9.9 vs 22.3 %, p = 0.034), simultaneous tuberculosis other than of the spine (0 vs 47.9 %, p < 0.001), and positive results in the interferon-gamma release assay (27.6 vs 79.2 %, p < 0.001)." (PMID 27733126, 2016). "Currently, there are two types of interferon-gamma release assays (IGRAs) in use for the detection of tuberculosis (TB) infection, the QuantiFERON-TB Gold In-Tube test (GFT-GIT) and T-SPOT.TB." (PMID 27258377, 2016). "Previous studies have shown that DNA-based or rBCG vaccines encoding TB-Ag85A can generate responses which induce antigen-specific IFNγ+ T cell populations, circulating titers of anti-Ag85A IgG, and which reduce virulent M. tuberculosis burdens in murine lungs and spleens." (PMID 26393347, 2015). "Comparisons of progression of tuberculosis in HIV-infected patients with interferon-gamma release assay testing." (PMID 25938227, 2015).
tuberculosis (continued). "Interferon-gamma Release Assays (IGRAs) significantly increases the possibility for early diagnosis of tuberculosis, but IGRAs alone cannot discriminate active TB from LTBI." (PMID 26643453, 2015). "The serum level showed normal value of tuberculosis antigen-specific interferon-gamma assay (TB IFN-γ) and angiotensin converting enzyme." (PMID 26674186, 2015). "Previous meta-analyses regarding the performance of interferon-gamma release assays (IGRAs) for tuberculosis diagnosis in children yielded contrasting results, probably due to different inclusion/exclusion criteria." (PMID 24564486, 2014). "The whole blood Quantiferon assay (WBA) was originally designed as a tool for diagnosis of tuberculosis, and detects cytokine (IFNγ) concentrations in plasma supernatants after 16–24 hours of incubation with antigen." (PMID 25275531, 2014). "Diagnostic tests in vitro using whole blood to assess the production of interferon-gamma (IFN -γ) by previously sensitized lymphocytes were developed in order to assist the diagnosis of tuberculosis (TB)." (PMID 24904240, 2014). "Interferon-gamma release assays have emerged as a more specific alternative to the tuberculin skin test (TST) for detection of tuberculosis (TB) infection, especially in Bacille Calmette-Guérin (BCG) vaccinated people." (PMID 25012075, 2014). "IFNγ has been shown to play a pivotal role in lung granuloma formation in murine models of tuberculosis." (PMID 25386143, 2014). "The screening for LTBI by means of the tuberculin skin test (TST) or whole blood interferon-gamma release assays (IGRAs) and the administration of chemoprophylaxsis have been shown to be effective for prevention to develop active tuberculosis." (PMID 24102039, 2013). "IFNγ expression was comparable between children with tuberculosis and LTBI after in vitro re-stimulation with M. tuberculosis-specific PPD and also for stimulation with staphylococcal superantigen SEB (data not shown)." (PMID 23613882, 2013). "IP-10 and MIG are both induced by IFNγ, which is a key molecule in the Type 1 response in human tuberculosis and is used as readout in IGRA assays." (PMID 23469125, 2013). "It acts as an effector molecule for interferon-gamma, which is essential for anti-tuberculosis immune response." (PMID 23874452, 2013). "Since IFNγ and miRNA expression varied between individuals we also compared expression of IFNγ and miR-29a in individual children with tuberculosis under chemotherapy and after recovery." (PMID 23613882, 2013). "Animal models and human genetic studies point towards a crucial role of IFNγ expressing T helper type (TH) 1 cells in protective host immunity against tuberculosis." (PMID 23613882, 2013). "Induction of an IFNγ response is used as a biomarker of successful vaccination in the assessment of new tuberculosis (TB) vaccines." (PMID 24710359, 2012). "The Mycobacterium tuberculosis (Mtb)-specific T-cell interferon gamma release assays (IGRAs) are useful in detecting Mtb infection but perform poorly at distinguishing active tuberculosis disease (ATB) and latent tuberculosis infection (LTBI)." (PMID 23272100, 2012). "While many North American healthcare institutions are switching from Tuberculin Skin Test (TST) to Interferon-gamma release assays (IGRAs), there is relatively limited data on association between occupational tuberculosis (TB) risk factors and test positivity and/or patterns of test discordance." (PMID 22916197, 2012). "Interferon-gamma release assays (IGRAs) are increasingly used in the tuberculosis (TB) screening of health care workers (HCWs)." (PMID 22537915, 2012). "The usefulness of interferon-gamma (IFN-γ) release assays for tuberculosis screening before tumor necrosis factor-alpha (TNF-α) antagonists and for monitoring during treatment is a contraversial issue." (PMID 22709461, 2012).
tuberculosis (continued). "There is a paucity of data on the pulmonary immune-compartment interferon gamma (IFNγ) response to M. tuberculosis, particularly in settings of high tuberculosis (TB) prevalence and in HIV-coinfected individuals." (PMID 22778764, 2012). "The aim of the present work was to evaluate the usefulness of the interferon-gamma release assays (IGRAs): QuantiFERON-tuberculosis (TB) Gold-In-Tube test (QFG) and T-SPOT.TB for the diagnosis of LTBI in a diverse cohort of HIV-infected patients." (PMID 22849726, 2012). "An evaluation of the IFNγ response determined using the refined ELISPOT readout as a potential correlate of protection against tuberculosis, or as a biomarker predictive of the progression of tuberculosis disease, should be investigated further." (PMID 24710359, 2012). "Interferon-gamma release assays (IGRA) are used for tuberculosis (TB) screening in healthcare workers (HCWs)." (PMID 21929799, 2011). "The tuberculosis-specific interferon-gamma release assay (IGRA) as an alternative screening for latent TB has been adopted so eagerly by the clinical community, as to interfere with the proper investigation of its predictive value." (PMID 22081766, 2011). "Interferon-gamma (IFN-γ) Release Assays (IGRA) are more specific than the tuberculosis skin test (TST) in the diagnosis of latent tuberculosis (TB) infection (LTBI)." (PMID 20210999, 2010). "A 14-week pregnant patient with recent exposure to a case of active tuberculosis was found to have a positive interferon-gamma assay." (PMID 22567257, 2010). "IFNγ in coordination with IL10 plays a key role in protective immunity against M. tuberculosis by regulating effector responses in tuberculosis." (PMID 20041183, 2009). "Variability in interferon-gamma release assays (IGRAs) results for tuberculosis has implications for interpretation of results close to the cut-point, and for defining thresholds for test conversion and reversion." (PMID 20041113, 2009). "IFNγ is a crucial mediator of protection against tuberculosis which strongly depends on T helper type-1 immunity." (PMID 19440342, 2009). "In this study, we assessed the sensitivity of Interferon gamma release assay (IGRA) in active tuberculosis patients who were positive for HIV infection and compared it with that of tuberculin skin test (TST)." (PMID 19479058, 2009). "In particular, the development and introduction in clinical practice of the interferon-gamma release assays (IGRAs) has open new perspectives for the detection of tuberculosis (TB) infection." (PMID 19365543, 2009). "The main goal of our study was to establish the value of IFNγ responses to CFP-10 as prognostic marker of tuberculosis disease development." (PMID 20011589, 2009). "The objective of the current study was to analyze the frequency of cytokine gene polymorphisms linked to high and low responder phenotypes (IFNγ +874 Thi→Alo and IL10 −1082 Glo→Ahi) in tuberculosis patients." (PMID 19274101, 2009). "Interferon-gamma release assay to detect tuberculosis (TB) infection from whole blood was tested in Hanoi, Viet Nam." (PMID 19450241, 2009). "There are limited data comparing the performance of the two commercially available interferon gamma (IFN-γ) release assays (IGRAs) for the diagnosis of tuberculosis (TB) in children." (PMID 18612425, 2008). "In 27 subjects diagnosed with active tuberculosis, the median [range] percentage of interferon-gamma synthetic CD4+ lymphocytes was 2.77% [0–23.93%] versus 0% [0–2.10%] in 15 negative for active infection (p<0.0001)." (PMID 18092001, 2007). "Our limitation is that only one regulatory factor was assessed in relation to the interferon-gamma assay; there are indeed many cytokines related to homeostatic mechanisms balancing responses to specific tuberculosis antigens." (PMID 17726533, 2007).